BMP5 (bone morphogenetic protein 5)
Diseases named in the same sentence as BMP5 in open-access papers (continued):
Sharing a sentence is not in itself a finding about the gene and the disease.
cancer (continued). "In this mining study, we used several online bioinformatics platform and web tools to systematically analyze the expression, mutations and CNAs, correlated genes, and prognostic value of BMP5 in human various cancers." (PMID 31973134, 2020). "Here, our findings validate the co-expression significance of BMP5 with its predicted functional protein partners in several cancers." (PMID 31973134, 2020). "The present findings also reveal the importance of BMP5 expression and possible BMP5-related pathways in human various cancers progression." (PMID 31973134, 2020). "We transact a multi-omics analysis to understand the potency of BMP5 as an oncogene or prognostic marker gene in different cancers." (PMID 31973134, 2020). "We also investigated the genes co-altered with BMP5 in relation to the five cancer types with high BMP5 expression." (PMID 31973134, 2020). "In cancer cells, the TGFB2 and BMP2&4 ligands are implicated with promoting EMT, whereas BMP5 and BMP7 are inhibit basal and/or TGF-β-induced EMT." (PMID 25972361, 2015). "The BMP5 gene was initially discovered during bone development, and recent research on the role of BMP5 in mammalian reproductive performance is limited and has focused mainly on its role in promoting apoptosis and treating cancer." (PMID 41398643, 2025). "Additionally, PCR results reveal that PSME2 and PSMB8 are highly expressed in cancer tissues, while BMP5 and BCL2 are more highly expressed in normal tissues." (PMID 41403941, 2025). "Then we deliberately modulated the BMP5 level and monitored the migration/invasion of cancer cells." (PMID 35054776, 2022). "It has been determined that miR-32 expression and CRC lymphatic invasion and metastasis are correlated by the cancer genome atlas (TCGA), and a negative association was also observed between miR-32 and bone morphogenetic protein 5 (BMP5)." (PMID 36428637, 2022). "This consistent trend in BMP5 expression in cancers suggests a commonality among different cancer types, where BMP5-related molecular pathways may be functional." (PMID 31973134, 2020). "We aimed to find the potential signalling mechanism involved with BMP5 expression in cancers." (PMID 31973134, 2020). "Collectively, this data-driven study demonstrates the correlation of BMP5 expression with patient survival and identifies the involvement of BMP5 pathways that may serve as targets of a novel biomarker for various types of cancers in human." (PMID 31973134, 2020). "Indeed, multifunctional signaling molecules such as BMPs have attracted attention in cancer research, and BMP-5 does have a role in cancer." (PMID 32050622, 2020). "To address the inconsistent correlation of BMP5 expression with patient survival and molecular function of BMP5 in relation to cancer progression, we performed a systematic study to determine whether BMP5 could be used as a prognostic marker in human cancers." (PMID 31973134, 2020). "Next, we generated BMP5 mRNA expression (RNA Seq V2) in 26 cancer studies from the cBioPortal web." (PMID 31973134, 2020). "The ONCOMINE database was queried for BMP5 expression in cancer and normal tissues." (PMID 31973134, 2020). "Likewise down-regulation of BMP5 has also been reported in other types of cancer such as adrenocortical carcinoma." (PMID 31973134, 2020). "However, our results clearly demonstrate that Bmp5 inactivation alone is sufficient to significantly delay cancer development with an efficiency similar to BMP pathway inhibition, identifying this ligand as a central player in the process." (PMID 32894216, 2020). "Genetic alterations of BMP5 in different cancer were studied by utilizing the cBioPortal database." (PMID 31973134, 2020). "Overall, our analysis may provide valuable insights into BMP5 as a novel biomarker and a potential therapeutic target for various human cancers and thus, will assist in transforming genomic knowledge into clinical practice." (PMID 31973134, 2020).
cancer (continued). "We found that BMP5 is frequently down-regulated in our queried cancer types." (PMID 31973134, 2020). "Finally, we determined the genes correlated with BMP5 in five types of cancer (breast, lung, colorectal, bladder, and ovarian) in which this TGF-β family member is significantly down-regulated by using R2 platform." (PMID 31973134, 2020). "BMP5 somatic missense mutations are present in 7.7% of colorectal cases and reduction in BMP5 through loss of function or damaging nonsynonymous variants has been linked to disease progression in cancer." (PMID 34069790, 2021). "Thus, these predicted interacting protein partners of BMP5 might be involved in the regulation of BMP5-mediated cancer progression and prognosis." (PMID 31973134, 2020). "Therefore, these systemic analyses eventually determine whether BMP5 expression can be used as a biomarker for the prognosis of human cancer." (PMID 31973134, 2020). "Subgroup-specific genes with strong effects on overall survival and high MIFs in the proposed weighted model involve the following cancer-related genes: ADH1C, BMP5, LCN2 and PLOD2 in GSE31210, CST1 in GSE37745, as well as AREG and COL4A3 in GSE29013." (PMID 34876106, 2021). "This allowed the selection of the key EMT-correlated genes that uncover functional implications in cancer; this is the case of direct correlation of NOX4 with DACT3 and SFRP1 and inverse correlation of NOX4 and BMP5." (PMID 34073426, 2021). "We utilized databases such as ONCOMINE, GENT, The Cancer Genome Atlas (TCGA) through UALCAN, GEPIA, and KM-Express to investigate the differential expression pattern of BMP5 in various cancer types and their counterparts." (PMID 31973134, 2020). "BMP5 and BMP6 play an important role in various cancers; both have been shown to induce apoptosis." (PMID 29986714, 2018).
hematological neoplasms (1 paper, 2024). "Looking at the group of “overlapping genes” that were differentially expressed in all hematological neoplasms, we found candidates crucially involved in osteogenesis and hematopoiesis, such as BMP5 (Bone morphogenetic protein 5)." (PMID 38893194, 2024).
infection (1 paper, 2019). The state of being infected such as from the introduction of a foreign agent such as serum, vaccine, antigenic substance or organism. "The BMP5 shRNA infection is capable of reverse FoxC1-induced SGC fate." (PMID 30894517, 2019).
BMP5 also shares sentences with these, for which no sentence is quoted: myeloma (5 papers); adrenocortical tumor (2); colorectal adenocarcinoma (2); melanoma (2); skin cancer (2); adenocarcinoma (1); Barrett esophagus (1); bladder tumors (1); glioblastoma (1); head and neck squamous cell carcinoma (1); hepatoma (1); hip osteoarthritis (1); Invasive ductal carcinoma (1); knee osteoarthritis (1); leiomyosarcoma (1); liposarcoma (1); orofacial cleft (1); sarcoma (1); spondyloarthropathy (1); systemic lupus erythematosus (1); tooth agenesis (1).